Y_RNA (Y RNA )
Gene: Miscellaneous RNA gene on chromosome 14 (49,592,236 to 49,592,337, reverse strand). Ensembl gene ENSG00000252919.
Homologues: Orthologues: macaque Y_RNA (87% identical), pig Y_RNA (78% identical). Paralogues in human: Y_RNA (91% identical), RNY3 (90% identical), Y_RNA (90% identical), Y_RNA (89% identical), RNY3P1 (88% identical), Y_RNA (88% identical), Y_RNA (87% identical), RNY3P14 (86% identical), Y_RNA (86% identical), RNY3P11 (85% identical), RNY3P9 (85% identical), Y_RNA (85% identical), and 95 more.